AIM2 (absent in melanoma 2)
Diseases named in the same sentence as AIM2 in open-access papers (continued):
Sharing a sentence is not in itself a finding about the gene and the disease.
retinitis (2 papers, 2020 to 2025). Inflammation of the retina. "We therefore initially compared MCMV-infected eyes of groups of retinitis-resistant MAIDS-4 mice with the MCMV-infected eyes of groups of retinitis-susceptible MAIDS-10 mice for detection and quantification of NLRP3, NLRP1b, or AIM2 transcripts." (PMID 41011779, 2025).
sarcoidosis (2 papers, 2020 to 2022). Sarcoidosis is a multisystemic disorder of unknown cause characterized by the formation of immune granulomas in involved organs. "The gene AIM2, functioning as a key factor of pyroptosis, was among the identified signatures for sarcoidosis, further emphasizing the role of cell death in sarcoidosis." (PMID 36203777, 2022).
Sézary syndrome (2 papers, 2023 to 2024). "Despite these abnormal patterns of expression, NLRP3 and AIM2 were equally expressed in the different groups, while NLRP1 expression was observed in Sézary syndrome skin compared to controls." (PMID 38397043, 2024). "Herein, to verify whether the expression of inflammasome components could be altered by Sézary syndrome, we assessed the expression of NLRP1, NLRP3, AIM2, IL-1B and IL-18 by immunohistochemistry in the epidermal and dermal layers of skin from SS patients." (PMID 36902104, 2023).
streptococcal infection (2 papers, 2019 to 2022). Any of the several infectious disorders caused by members of streptococcus, a genus of gram positive bacteria belonging to the family Streptococcaceae. "Although NLRP3 and AIM2 participate in IL-1β release by bmDCs and MΦ following infection by GBS and S. pneumoniae, the implication of NLRP1 and NLRC4 have not yet been described following streptococcal infection." (PMID 31262357, 2019).
vitiligo (2 papers, 2018 to 2020). Generalized well circumscribed patches of leukoderma that are generally distributed over symmetric body locations and is due to autoimmune destruction of melanocytes. "From the studied inflammasome-related genes only AIM2 was slightly elevated in vitiligo non-lesional skin." (PMID 30515176, 2018).
AA amyloidosis (1 paper, 2024). Secondary amyloidosis is a form of amyloidosis, that complicates chronic inflammatory disorders (mainly rheumatoid arthritis) and is characterized by the aggregation and deposition of amyloid fibrils composed of serum amyloid A protein, an acute phase reactant. "Here we report that ASC, the central component of the NLRP3, NLRC4 and AIM2 inflammasomes, coaggregates with SAA in tissues of patients with inflammation-associated AA amyloidosis." (PMID 39080493, 2024).
actinic keratosis (1 paper, 2017). A precancerous lesion of the skin composed of atypical keratinocytes. "Strong and moderate tumor cell specific expression of AIM2 was detected with immunohistochemistry (IHC) in sporadic human cSCCs in vivo, whereas expression of AIM2 was moderate in cSCC in situ (cSCCIS) and low or absent in actinic keratosis (AK) and normal skin." (PMID 28526809, 2017).
acute liver failure (1 paper, 2024). Rapid deterioration of liver function causing encephalopathy and coagulopathy. "Overall, AIM2 can serve as a promising treatment target for acute liver failure with age." (PMID 38429284, 2024).
adenovirus infection (1 paper, 2019). "During the early phase of an adenovirus infection, viral DNA is recognized by AIM2, which recruits ASC to form an inflammasome complex." (PMID 31849970, 2019).
Azoospermia (1 paper, 2024). Absence of any measurable level of sperm,whereby spermatozoa cannot be observed even after centrifugation of the semen pellet. "The alignment of gene expression results from tissue and blood samples, coupled with ROC curve analysis, suggests that investigating AIM-2, NLRC-4/IPAF, and IL-18 could serve as three potential biomarkers for predicting and differentiating the causes of azoospermia." (PMID 39712014, 2024).
bladder tumors (1 paper, 2022). "This additive effect results in the better efficacy of BCG immunotherapy in AIM2-high-expressed bladder tumors." (PMID 36386141, 2022).
bone marrow failure (1 paper, 2021). "Interestingly, mice deficient in AIM2 are protected from bone marrow failure after total body irradiation, demonstrating that AIM2 plays a role in apoptosis induction in the hematopoietic system." (PMID 34122418, 2021).
bovine tuberculosis (1 paper, 2025). "AIM2 upregulation by rFIP-nha was in line with observations for Mycobacterium bovis, the causative agent of bovine tuberculosis, which triggered interleukin 1β (IL-1β) in J774A.1 macrophages via the AIM2 inflammasome." (PMID 40356602, 2025).
bowel cancer (1 paper, 2023). "AIM2 gene mutations were frequent in patients with intestinal cancers." (PMID 37191444, 2023).
brain cancer (1 paper, 2025). A primary or metastatic malignant neoplasm affecting the brain. "Collectively, these studies highlighted the tumor suppressor function of AIM2 in brain cancers." (PMID 40002808, 2025).
bronchiolitis (1 paper, 2025). Inflammation of the bronchioles characterized by swelling of the bronchioles and mucus accumulation. "Histological scrutiny of lung slices from WT mice revealed bronchiolitis characterized by reduced alveolar air space and leukocyte infiltration, whereas lung slices from Aim2–/– mice exhibited a milder inflammatory response on day 7 after MPXV infection." (PMID 41225161, 2025).
Candidemia (1 paper, 2024). A form of invasive candidiasis where species of CANDIDA are present in the blood. "Collectively, these data show that activation of Aim2 transcription both in human and mice are one of the biomarkers of candidemia." (PMID 38918243, 2024).
Candidiasis (1 paper, 2024). Infection with the organism Candida. "Future work is also needed to delineate the role of AIM2 in mucosal Candidiasis." (PMID 38918243, 2024).
carotid atherosclerosis (1 paper, 2024). A thickening and loss of elasticity of the walls of carotid arteries that occur with formation of atherosclerotic plaques. "GSDMD, CASP1, NLRC4, AIM2, and IL18 were the key pyroptosis related genes, which might provide a new sight in the prevention of fatal strokes in advanced carotid atherosclerosis." (PMID 38167983, 2024).
celiac disease (1 paper, 2014). An autoimmune genetic disorder with an unknown pattern of inheritance that primarily affects the digestive tract. "Herein we report the isolation and characterization of AIM2, an anti-idiotype antibody elicited in a mouse model upon expression of the celiac disease-specific autoantibody MB2.8 (directed against the main disease autoantigen type 2 transglutaminase, TG2)." (PMID 25076134, 2014).
cerebrovascular diseases (1 paper, 2025). "Neurological diseases can be broadly categorized into cerebrovascular diseases, and neurodegenerative diseases, which are closely associated with the AIM2-caspase-1-GSDMD and NLRP3-caspase-1-GSDMD inflammasome signaling pathways." (PMID 39994107, 2025). "In cerebrovascular diseases, AIM2-mediated pyroptosis is a key pathological feature." (PMID 39994107, 2025).
cholestasis (1 paper, 2020). Impairment of the bile flow caused by obstruction within the liver, or outside the liver in the bile duct system. "In case of intahepatic cholestasis the activation was through NLRP3 whereas in case of extrahepatic cholestasis the activation was through AIM2." (PMID 32985571, 2020).
chronic heart failure (1 paper, 2023). "Moreover, non-NLRP3 inflammasomes, including NLRC4 and AIM2, contribute to the development of chronic heart failure." (PMID 37239853, 2023).
complication (1 paper, 2018). Any disease or disorder that occurs during the course of, or because of, another disease, treatment, or procedure. "Although no research related to the association between AIM2 methylation and diabetic vascular complications was found, AIM2 methylation level changes could affect the relationship between C-reactive protein and traumatic stress disorder." (PMID 30555415, 2018). "We should conduct a future study on a large sample concerning the relationship between AIM2 methylation and diabetic vascular complications." (PMID 30555415, 2018).
corneal infection (1 paper, 2019). A viral or bacterial infectious process affecting the cornea. "Since induction of inflammasomes triggers Caspase-1 activation, we next determined whether corneal infection with virulent HSV-1 strains would enhance the expression levels of one or several of the five major inflammasomes: NLRP3, NLRP6, NLRP12, IFI16/p204, and AIM2." (PMID 31367214, 2019).
diabetic foot ulcers (1 paper, 2022). "For example, the AIM2 inflammasome was activated in primary human keratinocytes due to intracellular S. aureus, which promoted cell pyroptosis and deregulation of the inflammatory response in nonhealing diabetic foot ulcers." (PMID 36120327, 2022).
disc degeneration (1 paper, 2021). "Moreover, knockdown of AIM2 ameliorates cellular DNA damage and disc degeneration in vitro and in vivo." (PMID 34239872, 2021). "In the in vivo experiments, AIM2 knockdown delayed disc degeneration, confirming the detrimental role of AIM2 in the progression of IDD." (PMID 34239872, 2021).
emphysema (1 paper, 2025). "Phenotype-specific therapy selection may include NLRP3 inhibitors for frequent exacerbators, AIM2 inhibitors for emphysema-dominant patients, and IL-33 pathway modulators for chronic bronchitis phenotypes." (PMID 41476973, 2025). "Type II alveolar epithelial cells show increased AIM2 inflammasome activation driven by mitochondrial DNA release, and circulating GSDMD fragments correlate with emphysema severity." (PMID 41476973, 2025).
endometritis (1 paper, 2021). An acute or chronic, usually bacterial infectious process affecting the endometrium. "We found NLRC4−/− and AIM2−/−, NOD1−/−, NOD2−/−, and GBPchr3−/− mice developed severe endometritis at day 56 pi." (PMID 34526512, 2021).
enteritis (1 paper, 2024). Inflammation of the small intestine. "Our findings also complement the previous findings by demonstrating the intestinal AIM2 inflammasome plays a double‐faced role in either rendering antitumor immunity or causing severe enteritis in response to chemotherapy." (PMID 38189627, 2024).
epilepsy (1 paper, 2025). A brain disorder characterized by episodes of abnormally increased neuronal discharge resulting in transient episodes of sensory or motor neurological dysfunction, or psychic dysfunction. "Laboratory studies from epilepsy have shown that the levels of inflammasomes (NLRP1, NLRP3, caspase 1, IL-1β, ASC, AIM2, gasdermin D, IL-18, intracellular calcium ion, sTNFr2) were also elevated." (PMID 40217546, 2025). "In particular, seizures were effectively controlled by decreasing the levels of AIM2 and NLRP3 and NLRP1 in a mouse model of kainic acid-induced epilepsy." (PMID 40217546, 2025). "In the kainic acid epilepsy mouse model, the results of the three studies collectively point to the signaling pathways of NLRP1, NLRP3, absent in melanoma 2 (AIM2), caspase 1, and ASC playing a key role in the activation of inflammation during epilepsy." (PMID 40217546, 2025).
extrahepatic cholestasis (1 paper, 2020). Impairment of the bile flow caused by an obstruction in the portion of the bile duct system located outside of the liver. "The extent of inflammasome activation was more or less same in case of both HCMV associated intrahepatic and extrahepatic cholestasis, but the initial activators were different; NLRP3 in case of IHC and AIM2 in case of EHC." (PMID 32985571, 2020).
gastric adenocarcinoma (1 paper, 2023). "Furthermore, these inflammasome‐dependent (early stage gastritis) and inflammasome‐independent (late stage gastric adenocarcinoma) mechanism(s) of action of AIM2 have potential to guide distinct therapeutic strategies against AIM2 at specific stages of the gastric carcinogenesis cascade." (PMID 36967659, 2023).
gastric disease (1 paper, 2023). "While members of the innate immune Toll‐like receptor and NLR families have been extensively investigated in the early stages of Helicobacter infection and gastric disease, here we focused on the cytosolic DNA sensor, AIM2." (PMID 36967659, 2023). "A possible explanation for the divergent functions of AIM2 in gastric disease is the cell‐type context of its expression." (PMID 36967659, 2023). "Overall, these data support our findings of Helicobacter‐associated elevated inflammasome activity in human gastric tissue biopsies, and suggest that AIM2 via inflammasomes promotes Helicobacter‐induced gastric disease." (PMID 36967659, 2023). "We therefore investigated whether AIM2 contributed to the pathogenesis of Helicobacter‐induced gastric disease." (PMID 36967659, 2023). "Therefore, whether AIM2 exhibits a potential inflammasome‐dependent role in gastric disease pathogenesis remains unclear." (PMID 36967659, 2023).
gastritis (1 paper, 2023). Inflammation of the stomach. "In summary, our current study suggests that the AIM2 inflammasome is a critical regulator of inflammation in the earlier stages of Helicobacter‐induced gastritis and associated epithelial hyperplasia." (PMID 36967659, 2023). "Conversely, AIM2 was recently implicated in downregulating T‐cell–mediated gastritis following Helicobacter infection, with the authors suggesting that this was independent of inflammasomes, despite classical read‐outs for inflammasome activation (e.g. caspase‐1 cleavage) not being assessed." (PMID 36967659, 2023). "Indeed, in GC, AIM2 upregulation was tumor intrinsic and restricted to the gastric epithelium, while we demonstrate here that AIM2 is upregulated in both gastric epithelial and immune cells in early stage Helicobacter‐related gastritis." (PMID 36967659, 2023). "We also note the possibility that these studies, which employ H. felis infections over different periods (i.e. 4 months versus 6 months), may further uncover multiple, and potentially contrasting, roles for AIM2 during various stages (e.g. gastritis, metaplasia) of chronic Helicobacter infection." (PMID 36967659, 2023). "To investigate a potential role for AIM2 in the initiating H. pylori–driven gastric inflammation stage of gastric carcinogenesis, we first measured AIM2 gene expression levels by quantitative real‐time PCR (qPCR) in patients with gastritis with and without Helicobacter infection." (PMID 36967659, 2023).
hand, foot and mouth disease (1 paper, 2020). A clinical syndrome that is usually caused by enterovirus infection, and that is characterized by fever, anorexia, and painful sores in the mouth, distal extremities, and/or other sites, including the buttocks. "Similarly, AIM2 expression is upregulated in neurons following infection with enterovirus A71, the causative agent of hand foot and mouth disease and AIM2 knockdown in a neuronal cell line led to decreased IL-1β cleavage and increased viral copy numbers." (PMID 33042875, 2020).
Helicobacter infection (1 paper, 2023). "Taken together, these data suggest that AIM2 is highly upregulated in the stomach among inflammasome‐associated PRRs during Helicobacter infection." (PMID 36967659, 2023). "Considering AIM2 has a well‐known function in the formation of inflammasome complexes, we next assessed whether AIM2 deficiency would impair the activation levels of the key inflammasome effector, caspase‐1, during chronic Helicobacter infection." (PMID 36967659, 2023). "Specifically, AIM2 contributed to augmented proliferation and apoptosis of both gastric epithelial and immune cells upon Helicobacter infection." (PMID 36967659, 2023). "Here, by coupling bona fide Aim2 knockout mice with a chronic Helicobacter infection model, together with clinical biopsies from infected patients, we reveal a driving role for AIM2 in Helicobacter‐induced gastric pathology." (PMID 36967659, 2023). "Considering the documented function of AIM2 in inflammasome complexes, we determined whether levels of caspase‐1 cleavage, a key indicator of inflammasome activity, was consistent with Helicobacter infection status in human gastric biopsies." (PMID 36967659, 2023).
hemorrhage (1 paper, 2024). Loss of blood from the vascular compartment to the exterior or into nonvascular body space as a result of rupture or severance of the blood vessels. "Taken together, serum AIM2 may be a potential biomarker for assessing hemorrhage severity and predicting DCI and 90-day functional outcome after aSAH." (PMID 38714826, 2024). "Our main findings are that serum AIM2 levels are independently related to hemorrhage severity, DCI and 90-day functional outcome after aSAH; moreover, serum AIM2 exhibits significantly effective predictive ability for DCI and poor prognosis at 90 days following aSAH." (PMID 38714826, 2024).
Herpesvirus infection (1 paper, 2025). "Herpesvirus infection activates the AIM2 inflammasome, which triggers cell pyroptosis and PANoptosis, and several viral proteins suppress AIM2 inflammasome activation to promote immune evasion and lytic replication." (PMID 40982560, 2025).
hidradenitis suppurativa (1 paper, 2023). A chronic suppurative and cicatricial disease of the apocrine glands occurring chiefly in the axillae in women and in the groin and anal regions in men. "Given the implication of the IL-1β pathway in the pathogenesis of syndromic hidradenitis suppurativa (HS), an autoinflammatory immune-mediated skin condition, the potential involvement of AIM2 was investigated." (PMID 36680007, 2023).
HIV-1 infection (1 paper, 2023). The type species of lentivirus and the etiologic agent of acquired immunodeficiency syndrome (AIDS). "To show evidences of early inflammasome sensing of HIV-1 in huNSG mice upon HIV-1 infection, we quantified mRNA expression of genes involved in inflammasome activation (NLRP3, NLRP1, NLRC4, AIM2, IFI16, ASC, CASP1, IL1Β, and IL18) in hCD45+ cells from multiple tissues collected at necropsy." (PMID 36800238, 2023).
hyperuricemia (1 paper, 2024). An abnormally high level of uric acid. "This study aimed to evaluate the role of absent in melanoma 2 (AIM2) inflammasome-mediated pyroptosis in the pathogenesis of acute gouty arthritis (AGA) and asymptomatic hyperuricemia(AHU)." (PMID 39100670, 2024). "Therefore, further investigations involving cultivated gene-silenced cells and gene knockout animal models are warranted to elucidate the precise contribution of the AIM2 inflammasome-mediated pyroptosis pathway in AGA and asymptomatic hyperuricemia." (PMID 39100670, 2024).
infertile (1 paper, 2024). "The ROC curve analysis indicated strong and significant predictive power of IL-18, AIM-2, and NLRC-4/IPAF gene expressions in differentiating between NOA vs. NS patients and NOA vs. OA infertile men." (PMID 39712014, 2024).
intestinal tumours (1 paper, 2017). "Our results show that PsV eradicates intestinal tumours of ApcMin/+ mice via activating the NLRP3 and AIM2 inflammasomes, leading to caspase-1-mediated tumour regression." (PMID 28397782, 2017). "Although normal epithelial cells express both NLRP3 and AIM2 innate immune receptors, we observed significant pyroptosis primarily in intestinal tumour cells but not normal epithelial cells." (PMID 28397782, 2017).
Kawasaki disease (1 paper, 2023). A rare inflammatory disease characterized by an acute febrile, systemic, self-limiting, medium-vessel vasculitis primarily affecting children. "Wang Z, Wang Q, Jin J, Rong X, Wu T, Qiu H, Wu R. The diagnostic role of AIM2 in Kawasaki disease." (PMID 37848930, 2023).
laminopathies (1 paper, 2021). "On the other hand, the AIM2 inflammasome has been shown to be activated after pharmacological alterations of the nuclear envelope integrity compatible with laminopathies." (PMID 34448355, 2021).